NLGN4X (neuroligin 4 X-linked)
Diseases named in the same sentence as NLGN4X in open-access papers (continued):
Sharing a sentence is not in itself a finding about the gene and the disease.
melanoma (2 papers, 2021 to 2024). A malignant, usually aggressive tumor composed of atypical, neoplastic melanocytes. "Here we focused on the role of NLGN4X (Neuroligin 4X) during melanoma progression and investigated its association with clinical parameters as well as its functional contribution to melanoma pathology." (PMID 38902533, 2024). "NLGN4X correlated inversely with melanoma stage and patient survival, underlining its potential as a prognostic marker for melanoma." (PMID 38902533, 2024). "In view of these findings, we propose that decreased amounts of NLGN4X are indicative of a metastatic melanoma phenotype and that loss of NLGN4X provides a novel mechanism for HIF induction." (PMID 38902533, 2024). "This might be due to progression of melanoma to a later stage, where additional mutations are acquired to cope with the stress induced by NLGN4X loss whereupon HIF1A activation becomes persistent." (PMID 38902533, 2024). "Furthermore, we showed that loss of NLGN4X reduced the neuronal gene signature in melanoma cells and triggered HIF signalling by VBP1 suppression." (PMID 38902533, 2024). "To analyse the correlation between NLGN4X and VBP1 in our melanoma samples, we performed Pearson correlation analysis and identified NLGN4X to significantly correlate with VBP1 (R = 0.581, P < 0.001)." (PMID 38902533, 2024). "Here we studied the postsynaptic cell adhesion molecule Neuroligin 4X (NLGN4X) and investigated its role in melanoma progression." (PMID 38902533, 2024). "To further explore the role of NLGN4X in melanoma patients we analysed the well characterised mRNA microarray file GSE19234." (PMID 38902533, 2024). "Histochemical analysis frequently revealed strong NLGN4X staining in samples of low stage primary melanoma when compared to samples of high stage primary melanoma." (PMID 38902533, 2024). "To investigate the role of NLGN4X expression in melanoma we acquired clinical melanoma samples from a US patient cohort comprising 249 samples." (PMID 38902533, 2024). "To test the effect of NLGN4X re-expression we chose to target metastasis-derived melanoma cells and to graft these cells to a recently developed human skin organoid model." (PMID 38902533, 2024). "We re-established NLGN4X expression in late stage melanoma lines and observed decreased tumour growth after transplantation to human skin organoids generated from pluripotent stem cells." (PMID 38902533, 2024). "We analysed histologic samples to assess the expression and predictive value of NLGN4X in human melanoma." (PMID 38902533, 2024). "To validate this finding, we acquired an additional 80 clinical melanoma patient samples from an Austrian cohort, which we subjected to immunohistochemical staining for NLGN4X and VBP1." (PMID 38902533, 2024). "The NLGN4X-dependent activation of HIF1A was essential for melanoma cell migration and invasion and, re-expression of NLGN4X in metastatic melanoma reduced tumour growth in human skin organoids." (PMID 38902533, 2024). "We have shown that late melanoma displays low NLGN4X expression." (PMID 38902533, 2024). "This study demonstrates compelling evidence for a link between NLGN4X-controlled neuronal differentiation and its ability to control HIF1A signalling in melanoma." (PMID 38902533, 2024). "In conclusion, we identified NLGN4X and its target VBP1 as novel melanoma markers down-regulated during melanoma progression." (PMID 38902533, 2024). "To further evaluate the role of NLGN4X and VBP1 in melanoma patients, we used mRNA microarray data from the TCGA consortium." (PMID 38902533, 2024). "Especially 1205Lu cells, which showed the strongest reduction in growth, also showed a higher number of melanoma cells with no detectable NLGN4X expression." (PMID 38902533, 2024).
melanoma (continued). "We first tested pairs of isogenic melanoma cell lines, which differ in outcome after transplantation to immunocompromised mice, for expression of NLGN4X: MCM1G (non-metastatic) and MCM1DLN (metastatic), as well as, WM793B (non-tumorigenic) and 1205Lu (metastatic) melanoma cell lines." (PMID 38902533, 2024).
triple-negative breast carcinoma (2 papers, 2017 to 2022). An invasive breast carcinoma which is negative for expression of estrogen receptor (ER), progesterone receptor (PR), and human epidermal growth factor receptor 2 (HER2). "Neuroligin 4 X-linked (NLGN4X) codes for a type-B carboxylesterase/lipase protein family member and is associated with poor relapse-free survival in triple-negative breast cancer." (PMID 36139405, 2022). "Evaluation of these bioinfomatic datasets results revealed that NLGN4X expression was higher in triple negative breast cancer cells, particularly the basal subtype and tissues versus non-triple-negative sets." (PMID 29244827, 2017).
alcohol dependence (1 paper, 2023). Physical and psychological dependence on alcohol. "As an example, NlGN4X, a gene on the X chromosome, has been associated with alcohol dependence in men only and may be a candidate gene for increasing the risk of developing AUD." (PMID 36960454, 2023).
developmental delay (1 paper, 2014). "NLGN4X, has been associated with X-linked mental retardation and X-linked autism spectrum disorders, and might explain the observed developmental delay." (PMID 25497574, 2014).
hyperlipidemia (1 paper, 2020). "We identified a novel 3,923 kb deletion within the Xp22.31 region (chrX: 5810838–9733877) containing STS, ANOS1, GPR143, NLGN4X, VCX-A, PUDP, and PNPLA4 in patient 1, who presented with KS, XLI, obesity, hyperlipidemia, and strabismus." (PMID 32670353, 2020).
lymph node metastasis (1 paper, 2017). "NLGN4X staining was also seen in respective lymph node metastasis." (PMID 29244827, 2017).
metastatic melanoma (1 paper, 2024). A melanoma that has spread from its primary site to another anatomic site. "Here, we identified NLGN4X as a novel prognostic marker for metastatic melanoma development in human patients." (PMID 38902533, 2024).
pancreatic cancer (1 paper, 2017). "Our previous studies using a selection from a combinatorial random peptide library against breast and pancreatic cancer cell lines identified several peptides mimicking neuroligin (NLGN-1, 3 and NLGN4X)." (PMID 29244827, 2017).
tumor (9 papers, 2009 to 2025). "NLGN4X is less over-expressed in GBM; however, the encoded epitope is over-presented on GBM tumours compared with healthy brain tissue." (PMID 41051649, 2025). "We further showed that re-expression of NLGN4X decreased tumour growth in a novel tumour model based on human foetal skin organoids generated from pluripotent stem cells." (PMID 38902533, 2024). "Unfortunately, the number of patients with available clinical data (discovery set = 19) was statistically too low to evaluate the association of NLGN4X and EDN3 expression level with tumor dissemination and patient survival." (PMID 34572907, 2021). "After processing of high resolution images, we could confirm that NLGN4X staining intensity decreased significantly in primary tumours of high pathologic disease stage, high T stage and positive N stage." (PMID 38902533, 2024). "In the present study, we show that NLGN4X is associated with non-metastatic tumour growth." (PMID 38902533, 2024). "Since the expression DCX and UCHL-1 may increase the ability of BPDCN tumor cells to disseminate to distant organs, globally worsening patient outcome, both genes, as already suggested for NLGN4X and EDN3, may be regarded as possible therapeutic targets to arrest BPDCN dissemination." (PMID 34572907, 2021). "ROBO1, KLK6, LIMK2, KLK7, NLGN4X, MBP, and NEDD9 expression levels were significantly higher in normal tissues than in tumors, demonstrating the possibility of being a tumor suppressor gene." (PMID 38137332, 2023). "As exemplified by PTPRZ1- and NLGN4X-specific T cells, their T cell receptors (TCR) were able to license transgenic T cells to exhibit cytotoxic activity towards target-expressing tumor cell lines, confirming natural processing within the tumor cells." (PMID 36303101, 2022). "This suggests that once NLGN4X is down-regulated, tumour cells adapt and do not tolerate its re-expression." (PMID 38902533, 2024). "Furthermore, we identified NLGN4X and VBP1 to play fundamental roles in HIF transcription factor stabilisation and tumour cell migration." (PMID 38902533, 2024). "The differential gene expression levels between the tumor and adjacent tissue indicated that the ROBO1, KLK6, LIMK2, KLK7, NLGN4X, MBP, and NEDD9 gene expression levels were higher in normal tissues than in tumors; however, EFNA1 was higher in the tumor than the normal ones." (PMID 38137332, 2023). "According to the changes of the expression status of differential molecules between the two networks, we identified the top 10 differential mRNAs (PRKAA2, NLGN4X, ST6GALNAC3, DGAT1, TRIB1, GRPR, and MLLT11) and lncRNAs (n339695, n378130, and n410438) in the tumor–endothelium interaction." (PMID 33681194, 2021). "First, we focused on the neuroligin 4 X (NLGN4X) and Endothelin 3 (EDN3) genes, two BPDCN network neural genes, aberrantly upregulated in BPDCN samples and already described in the literature as possibly involved in tumor progression." (PMID 34572907, 2021). "Secondly, at the light of literature findings, among the network-genes related to neurogenesis, the attention was focused on Neuroligin 4 X-linked (NLGN4X) and Endothelin-3 (EDN3), never reported before in BPDCN but already known to correlate with tumor aggressiveness." (PMID 34572907, 2021). "Of these, 8 genes showed a significant decrease in expression in tumor samples with this deletion relative to tumors samples without this deletion: ARSD, ARSE, MXRA5, PRKX, LOC729137, NLGN4X, HDHD1A, and STS." (PMID 19419571, 2009).
neurodevelopmental disorder (8 papers, 2015 to 2025). A behavioral and cognitive disorder with onset during the developmental period that involves impaired or aberrant development of intellectual, motor, or social functions. "Many subsequent studies have linked NLGN4X with neurodevelopmental disorders, and the recurrent theme is that the majority of affected probands are males." (PMID 32848696, 2020). "In humans, multiple genetic studies have implicated a significant role for NLGN4X in the susceptibility to several neurodevelopmental disorders." (PMID 26759715, 2016). "Although NLGN4-like KO mice provide insights into how this protein may function at synapses, because human NLGN4X and mouse NLGN4-like are divergent, there should be caution in linking mouse NLGN4-like studies with NLGN4X-associated neurodevelopmental disorders." (PMID 32848696, 2020).
neurological diseases (7 papers, 2016 to 2024). "This regulatory region in NLGN4X might have a role in modulating neuroligin biological function and, therefore, in causing or predisposing to neurological disorders." (PMID 27782075, 2016).
cancer (4 papers, 2016 to 2023). A tumor composed of atypical neoplastic, often pleomorphic cells that invade other tissues. "These suggest the role of NLGN4X as being essential for cancer cells survival." (PMID 29244827, 2017). "We also observed a positive significant (p < 0.05) correlation between the ESR1 gene expression level and NLGN4X expression in BRCA-Her2 and BRCA-LumB cancer patients and MBP expression in BRCA-LumA and -LumB patients." (PMID 38137332, 2023). "Given the promising role of NLGN4X and EDN3 as therapeutic targets and prognostic factors in cancer patients, their predictive value in the discovery set was evaluated." (PMID 34572907, 2021). "There was low expression of the NLGN4X protein in noncancerous samples; and high expression in carcinoma; expression was predominantly in the membrane or cytoplasm." (PMID 29244827, 2017).
psychiatric disorder (2 papers, 2020 to 2025). A disorder characterized by behavioral and/or psychological abnormalities, often accompanied by physical symptoms. "That is, our data suggested that maintaining adequate NLGN4X expression level is necessary for neuronal function, and its dysfunction caused psychiatric disorders including ASD/XLMR." (PMID 32873342, 2020).
NLGN4X also shares sentences with these, for which no sentence is quoted: schizophrenia (10 papers); cognitive disease (3); depression (3); fragile X syndrome (3); Tourette syndrome (3); genetic diseases (2); glioblastoma (2); acute lymphoblastic leukemia (1); Angelman syndrome (1); Ataxia (1); behavioral disorders (1); breast invasive carcinoma (1); dyschondrosteosis (1); ichthyosis (1); language disorder (1); learning disorder (1); metastatic tumor (1); microcephaly (1); Obesity (1); obsessive-compulsive disorder (1); Opitz GBBB syndrome, type I (1); Parkinson disease (1); pervasive developmental disorder (1); Phelan-McDermid syndrome (1); prostatic intraepithelial neoplasia (1); Rett syndrome (1); SESAME syndrome (1); Strabismus (1); tuberous sclerosis (1); velocardiofacial syndrome (1).
A further 1 disease shares a sentence with NLGN4X in 1 paper.